SLC9A4 (solute carrier family 9 member A4)
Description:
Electroneutral antiporter that exchanges sodium for protons or ammonium ions at the basolateral membrane of epithelia to regulate cell volume and intracellular pH upon hypertonic conditions (By similarity). As part of transcellular ammonia transport in renal tubules, mediates basolateral ammonium extrusion in the medullary thick ascending limb, regulating the corticopapillary ammonium gradient and overall renal acid excretion (By similarity). Mediates sodium:proton exchange in gastric parietal cells secondary to cAMP-dependent acid secretion and hyperosmolarity. Possibly coupled to chloride:bicarbonate antiporter, enables loading of parietal cells with sodium and chloride ions to maintain cell volume and normal gastric acid secretion (By similarity). Functions as a sodium sensor in neurons of organum vasculosum of the lamina terminalis where it regulates water intake in response to increased sodium concentration in body fluids (By similarity).
Synonyms: NHE4
Tractability: Antibody: its Gene Ontology location is reachable by antibodies, with high confidence; UniProt places it where antibodies can reach, with medium confidence; UniProt predicts a signal peptide or a membrane-spanning region; the Human Protein Atlas places it where antibodies can reach. PROTAC: it is named in the literature on targeted protein degradation; ubiquitination databases record sites on it.
Gene: Protein-coding gene on chromosome 2 (102,473,226 to 102,533,972, forward strand). Ensembl gene ENSG00000180251.
Subcellular location: Basolateral cell membrane; Apical cell membrane; Zymogen granule membrane
Subcellular location (Human Protein Atlas): Nucleoplasm; Plasma membrane
Pathways (Reactome):
Transport of small molecules: Sodium/Proton exchangers
Gene Ontology:
Molecular function: sodium:proton antiporter activity; antiporter activity
Biological process: regulation of intracellular pH; sodium ion import across plasma membrane; sodium ion transmembrane transport; transepithelial ammonium transport; monoatomic cation transport; proton transmembrane transport; regulation of pH; sodium ion transport; transmembrane transport
Cellular component: apical plasma membrane; basolateral plasma membrane; plasma membrane; zymogen granule membrane; membrane
Genetic constraint (gnomAD): Loss-of-function variants: 57 observed, 66.83 expected, observed/expected ratio (o/e) 0.85, 90% interval 0.69 to 1.06. The upper end of that interval is the gene's LOEUF score, 1.06, which puts it in group 4 of 6, group 1 being the genes least tolerant of losing a copy. Missense variants: 1,077 observed, 1,028.2 expected, observed/expected ratio (o/e) 1.05, 90% interval 1 to 1.1. Synonymous variants: 390 observed, 386.97 expected, observed/expected ratio (o/e) 1.01, 90% interval 0.93 to 1.1.
Homologues: Orthologues: chimpanzee SLC9A4 (99% identical), macaque SLC9A4 (97% identical), dog SLC9A4 (89% identical), rabbit SLC9A4 (85% identical), pig SLC9A4 (85% identical), mouse Slc9a4 (83% identical), rat Slc9a4 (83% identical), guinea pig SLC9A4 (75% identical), tropical clawed frog slc9a4 (56% identical), Drosophila melanogaster Nhe2 (37% identical), Caenorhabditis elegans nhx-2 (28% identical), Caenorhabditis elegans nhx-6 (28% identical), and 3 more. Paralogues in human: SLC9A2 (54% identical), SLC9A1 (40% identical), SLC9A3 (34% identical), SLC9A5 (33% identical), SLC9A7 (20% identical), SLC9A6 (20% identical), SLC9A9 (20% identical), SLC9A8 (17% identical), SLC9C2 (15% identical), SLC9C1 (13% identical).
Diseases named in the same sentence as SLC9A4 in open-access papers:
SLC9A4 is named in the same sentence as 15 diseases in open-access papers, as found by Europe PMC text mining. Sharing a sentence is not in itself a finding about the gene and the disease. The quoted sentences say what the papers report.
celiac disease (2 papers, 2021 to 2022). An autoimmune genetic disorder with an unknown pattern of inheritance that primarily affects the digestive tract. "This reduced IL-18 cytokine expression in celiac disease is consistent with the overall reduced expression of SLC9A4 observed among diabetic neutrophils in our study." (PMID 34134627, 2021).
colon carcinoma (2 papers, 2016 to 2021). "SLC9A4 is reported to exist in T84 human colon cancer cell, which occupied 43% of pH recovery after an acid intervention." (PMID 34917077, 2021).
Arthritis (1 paper, 2024). Inflammation of a joint. "The genes with the most significantly increased expression in the synovial tissues of the arthritis-protected Mg2800 diet group included Snora34, Gnrh1, Actc1, Nr4a3, and Slc9a4." (PMID 39683640, 2024).
asthma (1 paper, 2022). "Five genes previously reported in a genome-wide association study (GWAS) on asthma, including TSLP, SLC9A4, PSMB8, IGSF5, and IKZF4 were demonstrated association in the asthma vs. control analysis." (PMID 35524249, 2022). "The associations of IKZF4 and IGSF5 are only associated with obese asthma; and the association of SLC9A4 is only observed in non-obese asthma." (PMID 35524249, 2022). "In contrast to the associations of IKZF4 and IGSF5 seen in obese asthma, the genetic association of SLC9A4, encoded by the solute carrier family 9 member A4 gene, is only seen in non-obese asthma." (PMID 35524249, 2022). "Three of the genes delineated clear heterogeneous effects between obese asthma and non-obese asthma, with IKZF4 and IGSF5 showing association with obese asthma, and SLC9A4 with non-obese asthma." (PMID 35524249, 2022).
eczema (1 paper, 2021). "We identify rare exonic variants in DUSP1, NOTCH4, and SLC9A4 to be associated with eczema." (PMID 34785669, 2021). "The eczema associated variant rs61731289 is located within the cytoplasmic tail of SLC9A4." (PMID 34785669, 2021). "In our meta-GWAS on rare variants in eczema, we uncover disease-associated exonic variants in the genes encoding dual specificity phosphatase 1 (DUSP1), neurogenic locus notch homolog protein 4 (NOTCH4), and solute carrier family 9 member A4 (SLC9A4)." (PMID 34785669, 2021).
Graves disease (1 paper, 2021). Graves' disease is an autoimmune disorder that leads to overactivity of the thyroid gland (hyperthyroidism).It is caused by an abnormal immune system response that causes the thyroid gland to produce too much thyroid hormones. "In the thyroid, ATP4A and PTH2R variants were only found in Hashimoto’s disease, while SLC9A4 variants were only found in Graves’ disease." (PMID 34944008, 2021).
psoriasis (1 paper, 2022). An autoimmune condition characterized by red, well-delineated plaques with silvery scales that are usually on the extensor surfaces and scalp. "Other validated psoriasis susceptibility genes were ERAP2 (5q15), IL18R1 (2q12.1), LTB (12p13.31), IL1RL1 (2q12.1), CARD14 (17q25.3), and SLC9A4 (2q12.1)." (PMID 36425068, 2022). "In this study, we verified the psoriasis susceptibility genes IFIH1 (2q24.3), ERAP2 (5q15), IL18R1 (2q12.1), LTBR (12p13.31), IL1RL1 (2q12.1), CARD14 (17q25.3), and SLC9A4 (2q12.1)." (PMID 36425068, 2022).
cardiovascular disease (1 paper, 2021). "Another GWAS linked SLC9A4 with regulation of IL-33/ST2 (suppression of tumorigenicity 2, part of the IL-1R family) signaling, which has previously been implicated in both immune and inflammatory diseases, including cardiovascular disease." (PMID 34134627, 2021).
metabolic disease (1 paper, 2020). A congenital disorder (due to inherited enzyme abnormality) or acquired (due to failure of a metabolically important organ) disorder resulting from an abnormal metabolic process. "SLC9A4 corresponds to a group of Na+/H+ exchangers, which are expressed in the stomach, small intestine, colon, skeletal muscle and brain and it has been associated with metabolic diseases." (PMID 32822435, 2020).
tumor (1 paper, 2021). "The outcome of UALCAN showed that, except SLC9A4 and SLC9A6, the mRNA expression of other members prominently affected tumor stage and lymph node metastasis." (PMID 34759967, 2021).
SLC9A4 also shares sentences with these, for which no sentence is quoted: amyotrophic lateral sclerosis (1 paper); diarrhoea (1); Hashimoto’s disease (1); inflammatory bowel disease (1); Obesity (1).